GSDMD (gasdermin D)
Diseases named in the same sentence as GSDMD in open-access papers (continued):
Sharing a sentence is not in itself a finding about the gene and the disease.
ulcers (3 papers, 2024 to 2025). "The vacA m2 allele showed a distinct ASC response in gastritis versus ulcer patients and was associated with increased GSDMD expression in ulcerative cases." (PMID 40563885, 2025). "In the infected patient groups, GSDMD expression changed simultaneously in 66.7% of the population in the presence of gastritis and synchronously in 80% of ulcer patients." (PMID 40563885, 2025). "Expression of both forms of GSDMD was decreased in 38.9% of infected gastritis patients, but this was seen in 70% of infected ulcer patients." (PMID 40563885, 2025). "It was found that both GSDMD−/− mice and WT mice in the modeled groups developed PG-like ulcers on their backs." (PMID 40034857, 2025). "This research elucidated that the relative mRNA expression of NLRP3 and GSDMD in stomach tissue had a significant upregulation in the ulcer group compared to the control group (P < 0.001 for each)." (PMID 38457071, 2024). "Notably, the vacA m2 allele was associated with a differential response in ASC expression among patients with gastritis and ulcers, correlating with increased GSDMD levels in ulcerative conditions." (PMID 40563885, 2025). "Our study exhibited that GSDMD expression is significantly upregulated in the ulcer group." (PMID 38457071, 2024).
uveal melanoma (3 papers, 2022 to 2025). A melanoma derived from melanocytes of the uveal tract. "Furthermore, data from the GEPIA2 database showed a positive correlation between GSDMD expression and overall survival (OS) in SKCM, and a negative correlation in ACC, LGG, and Uveal Melanoma (UVM)." (PMID 40491921, 2025).
abscess (2 papers, 2021 to 2025). An inflammatory process characterized by the accumulation of pus within a newly formed tissue cavity which is the result of a bacterial, fungal, or parasitic infection or the presence of a foreign body. "GSDMD deficiency resulted in larger abscesses, more bacterial colonization, exacerbated skin damage, and increased inflammatory cell infiltration." (PMID 34011393, 2021). "According to the available studies, the upregulation of GSDMD in lesional skin correlates with increased infiltration of immune cells, abscess formation, and the development of tunnels, all of which are hallmark features of HS." (PMID 41007405, 2025). "The abscess structure was dramatically attenuated in the GSDMD−/− mice treated with SB225002, nearly to the extent observed in the WT mice after S. aureus skin infection." (PMID 34011393, 2021). "The abscess structure from the GSDMD−/− mice was more severe than that from the WT mice on day 2 post-infection." (PMID 34011393, 2021). "The GSDMD−/− mice treated with SB225002 exhibited decreased abscesses and presented comparable levels to those of the WT mice." (PMID 34011393, 2021). "This suggests that GSDMD-induced pyroptosis may drive inflammation and serve as a key initiator of the tissue damage that leads to abscess and tunnel formation." (PMID 41007405, 2025). "The abscess structure was dramatically attenuated in the GSDMD−/− mice treated with MAB453." (PMID 34011393, 2021). "The GSDMD−/− mice formed significantly larger abscesses on days 2–9 than the WT mice." (PMID 34011393, 2021).
age-related macular degeneration (2 papers, 2021 to 2024). Age-related loss of vision in the central portion of the retina (macula), secondary to retinal degeneration. "Blocking pyroptosis by targeting the assembly of NLRP3 inflammasomes and GSDMD emerges as a potential therapeutic approach for addressing neuroinflammation and neurodegeneration-related conditions, including age-related macular degeneration (AMD) and Alzheimer’s disease." (PMID 39065688, 2024).
atrial fibrillation (2 papers, 2022 to 2025). A disorder characterized by an electrocardiographic finding of a supraventricular arrhythmia characterized by the replacement of consistent P waves by rapid oscillations or fibrillatory waves that vary in size, shape and timing and are accompanied by an irregular ventricular response. "GSDMD plays a pivotal pathogenic role in the development of atrial fibrillation (AF)." (PMID 40832143, 2025).
autoimmune hepatitis (2 papers, 2022 to 2023). Hepatitis caused by autoantibodies. "IMPORTANCE Our study provides the first direct clues to the protective role of gasdermin D (GSDMD) in autoimmune hepatitis (AIH)." (PMID 35972273, 2022).
brain inflammation (2 papers, 2022 to 2023). "Our results support the crucial role of GSDMD in mediating hyperoxia-induced brain inflammation." (PMID 37679766, 2023).
cardiac arrest (2 papers, 2020). Cessation of breathing and/or cardiac function. "In this study, we established a cardiac arrest model and detected NLRP3 inflammasome and GSDMD in myocardial tissues after global myocardial I/R injury." (PMID 32782443, 2020).
cholestasis (2 papers, 2023 to 2024). Impairment of the bile flow caused by obstruction within the liver, or outside the liver in the bile duct system. "Subsequently, the elevation of TNFRSF12A triggers hepatocyte pyroptosis by the NFκB/Caspase-1/GSDMD signaling in cholestasis." (PMID 36690641, 2023). "Previous studies in the context of cholestasis demonstrated that bile acids induce TNFRSF12A expression, subsequently initiating hepatocyte pyroptosis through the nuclear factor κB (NF-κB)/CASP1/gasdermin (GSDMD) signaling pathway." (PMID 39232561, 2024).
chronic prostatitis (2 papers, 2023 to 2024). An infectious or non-infectious chronic inflammatory process that affects the prostate gland. "In conclusion, the P2X7R-NEK7-NLRP3 axis could promote GSDMD-NT-mediated prostate epithelial cell pyroptosis and chronic prostatitis development, and disulfiram may be an effective drug to treat chronic prostatitis." (PMID 38993566, 2024). "P2X7R-NLRP3 axis could induce prostate epithelial cell pyroptosis by converting GSDMD to GSDMD-NT, which formed cell membrane pores and permitted IL-1β and IL-18 production and leakage to promote chronic prostatitis development." (PMID 38993566, 2024). "Importantly, we found that disulfiram could ameliorate chronic prostatitis by inhibiting GSDMD-NT-mediated prostate epithelial cell pyroptosis and Th17 cell differentiation, and targeting P2X7R and pyroptosis may be effective in chronic prostatitis treatment." (PMID 38993566, 2024).
corneal infection (2 papers, 2023 to 2024). A viral or bacterial infectious process affecting the cornea. "These outcomes show that the GSDMD and NLRP3 protein expressions play an important role in S. pseudintermedius-mediated corneal ulceration." (PMID 38515339, 2024).
coronary heart disease (2 papers, 2021 to 2023). "Consistently, the mRNA expression of caspase-4 and gasdermin D was upregulated in peripheral blood mononuclear cells from patients with coronary heart disease." (PMID 33981234, 2021).
cutaneous leishmaniasis (2 papers, 2023 to 2024). Leishmaniasis affecting the skin. "Next, we assessed the activation of GSDMD in the skin of patients with cutaneous Leishmaniasis." (PMID 36828815, 2023).
endometrial tumor (2 papers, 2020 to 2025). "In the mouse model, H2 exposure significantly inhibited endometrial tumor growth compared to controls (p < 0.01) and increased expression of NLRP3, caspase-1, and GSDMD, confirming the promotion of pyroptosis." (PMID 41140697, 2025).
endometrioid carcinoma (2 papers, 2020 to 2024). "Elevated expression of GSDMD was observed in the tissues of patients with endometrioid carcinoma; however, other studies have shown that the tumor volume in groups treated with hydrogen-rich water was reduced by GSDMD-mediated pyroptosis compared to that in control mice." (PMID 33348858, 2020).
endometriosis (2 papers, 2025). The growth of functional endometrial tissue in anatomic sites outside the uterine body. "In patients with endometriosis, peritoneal fluid washings demonstrate higher levels of caspase 1, IL-1β and gasdermin D (GSDMD) compared with healthy individuals." (PMID 41148809, 2025). "Compared to normal human endometriosis cells, the expression of BAK1, CHMP2A, GPX4, and GSDMD was upregulated, whereas the expression of CHMP2B, IRF2, and TIRAP was negatively regulated in UCEC cells." (PMID 40535818, 2025).
geographic atrophy (2 papers, 2021 to 2022). "Gasdermin D levels have been shown to be elevated in the RPE in human eyes with geographic atrophy." (PMID 34071220, 2021).
Granuloma (2 papers, 2023). A compact, organized collection of mature mononuclear phagocytes, which may be but is not necessarily accompanied by accessory features such as necrosis. "Histological sections of granulomas from animals naturally infected with M. bovis displayed the markers of cleaved gasdermin D in macrophages and multinucleated giant cells from granulomas in the lymph nodes and in the tissue adjacent to the granuloma." (PMID 37626889, 2023). "Many other granuloma models have had contrasting conclusions as to whether caspase-1/11 and gasdermin D contributed to granuloma biology." (PMID 37865673, 2023).
head and neck squamous cell carcinoma (2 papers, 2022). A squamous cell carcinoma that arises from any of the following anatomic sites: lip and oral cavity, nasal cavity, paranasal sinuses, pharynx, larynx, and salivary glands. "Here, we report that GSDMD is overexpressed in different types of tumours, including head and neck squamous-cell carcinoma, and it promotes the sensitivity of tumour cells to cisplatin." (PMID 35289335, 2022). "For example, in pancreatic ductal adenocarcinoma (PDA) and head and neck squamous cell carcinoma (HNSCC), inflammasomes of tumor-associated macrophages activate caspase-1 and mediate the cleavage of GSDMD and the release of mature IL1β, resulting in the suppression of CD8+ T cells." (PMID 36199426, 2022).
kidney stone (2 papers, 2024 to 2025). "Here, we found that gasdermin D (GSDMD)-mediated pyroptosis occurred in both patients and mice with calcium oxalate (CaOx) nephrolithiasis, and the expression levels of NOD-like receptor protein 3 (NLRP3) and GSDMD were associated with the severity of kidney stones." (PMID 40384863, 2025). "Together, these findings strongly suggest that GSDMD-mediated pyroptosis promotes tubular cell damage, inflammatory response, and crystal deposition, thereby accelerating kidney stone progression." (PMID 40384863, 2025). "All these results suggest that the NLRP3/GSDMD axis is activated in the kidneys of patients and mice with renal calculi, indicating the potential involvement of pyroptosis in the pathogenesis of CaOx kidney stones." (PMID 40384863, 2025). "Here, we found that GSDMD-mediated pyroptosis was activated in RTECs from patients with kidney stones and mouse models, and that the expression of pyroptosis-associated proteins was positively correlated with the expression of adhesion molecules in CaOx kidney stones." (PMID 40384863, 2025). "Furthermore, to investigate the role of NLRP3/GSDMD-mediated pyroptosis in renal stone formation, we conducted qRT-PCR assays on blood samples (20 normal individuals vs. 20 kidney stone patients)." (PMID 40384863, 2025). "Our collective results indicate that the NLRP3/GSDMD signaling pathway is involved in the upregulation of inflammatory factors and adhesion molecule-related proteins, and the absence of GSDMD hinders renal inflammation and pyroptosis-induced cell death, thereby attenuating kidney stone formation." (PMID 40384863, 2025). "To further investigate the mechanism of cellular damage during kidney stone formation, we focused on NLRP3/GSDMD-mediated pyroptosis." (PMID 40384863, 2025). "Quantitative analysis revealed significantly higher mRNA expression of NLRP3, GSDMD, and crystal adhesion factor (cluster of differentiation 44, CD44) in kidney stone samples than in normal samples." (PMID 40384863, 2025). "Our study found that CHMP4B expression levels were elevated in a mouse model of Gly-induced kidney stones but not sufficient to resist GSDMD-mediated pyroptosis." (PMID 40384863, 2025).
Legionella infection (2 papers, 2019 to 2025). "Pyroptosis was rapidly induced within 1 h of T4SS+ or T4SS+Δ7 Legionella infection, as evidenced by GSDMD processing into its active p32 fragment." (PMID 40530878, 2025). "Collectively, these data indicate that in addition to T4SS effector-triggered apoptosis, DCs activate caspase-11- and GSDMD-dependent pyroptosis early during Legionella infection." (PMID 40530878, 2025). "In contrast, we observed more GSDMD p32 and the absence of p23 and p43 fragments in DCs infected with T4SS+Δ7 Legionella, suggesting that caspases-3 and -7 limit the formation of active GSDMD p32 during T4SS+Legionella infection." (PMID 40530878, 2025).
leukemia (2 papers, 2022 to 2024). A malignant (clonal) hematologic disorder, involving hematopoietic stem cells and characterized by the presence of primitive or atypical myeloid or lymphoid cells in the bone marrow and the blood. "In this study, we found that curcumin induced the expression of NLRC4, AIM2, and IFI16 inflammasomes by upregulated ISG3 transcription factor complex in leukemia cell U937, which activates caspase 1 and promotes cleavage of GSDMD." (PMID 35435150, 2022). "We detected the expression of GSDMD in different leukemia cells." (PMID 35435150, 2022). "To further explore the role of GSDMD in curcumin anti-leukemia, we used RNA interference technology to inhibit the expression of GSDMD in U937 cells and analyzed whether it could change the sensitivity of U937 cells to curcumin." (PMID 35435150, 2022). "It was also found that curcumin could promote the expression of GSDMD in a variety of leukemia cells." (PMID 35435150, 2022). "Our results demonstrated that pyroptosis may be a potential new mechanism of curcumin treating leukemia, and GSDMD is a biomarker to evaluate curcumin sensitivity in the leukemia therapy." (PMID 35435150, 2022). "In our studies, we found that heterologously overexpressing GSDMD enhanced sensitivity of K562 cell to curcumin, and inhibition of GSDMD with shRNA in U937 cells enhance curcumin anti-leukemia effect, indicating that the sensitivity of leukemia cells to curcumin is clearly related to pyroptosis." (PMID 35435150, 2022). "Curcumin could induce cleavage of GSDMD in some leukemia cell lines such as MV4-11, NB4, Kasumi, and THP1." (PMID 35435150, 2022). "Compared with the control group, proliferation inhibition of GSDMD-knockdown group is significantly lower at the same concentration of curcumin, indicating GSDMD could enhance anti-leukemia effect of curcumin." (PMID 35435150, 2022). "Thus, pyroptosis may be a potential new strategy for treating leukemia, and GSDMD is a biomarker to evaluate curcumin sensitivity in the leukemia therapy." (PMID 35435150, 2022). "In addition, the anti-leukemia effect of curcumin is affected by the expression of GSDMD." (PMID 35435150, 2022). "In addition, we also found that the expression of GSDMD varied greatly in leukemia cell lines." (PMID 35435150, 2022). "In this study, we demonstrated that curcumin induced the expression of AIM2, IFI16, and NLRC4 inflammasomes in leukemia cells U937 by increasing the expression levels of ISG3 transcription factor complex, which activated caspase 1, promoted cleavage of GSDMD, and induced pyroptosis." (PMID 35435150, 2022).
mastitis (2 papers, 2025 to 2026). Inflammation of breast tissue during lactation or postpartum due to an obstructed duct or infection. "Pathway enrichment analysis indicated that NLRP3, caspase-1 (CASP1), and GSDMD were enriched in the NOD-like receptor signaling pathway and were closely associated with mastitis." (PMID 41897529, 2026). "Mechanistically, C3Gal regulated mastitis progression by inhibiting PANoptosis activation, and suppressing gasdermin D N‐terminal activity to regulate BMB damage during mastitis." (PMID 40552401, 2025). "In conclusion, GSDMD is binding target, C3Gal effectively regulates TJ damage between cells during mastitis by directly and stably binding to GSDMD and inhibiting NT activity." (PMID 40552401, 2025). "However, GSDMD−/− mice exhibited less severe tissue damag during mastitis, with reduced immune cell infiltration and more intact alveolar structures than in TLR4−/− mice." (PMID 40552401, 2025). "This led us to the hypothesize that C3Gal may inhibits the NT‐mediated pore‐forming activity of GSDMD, thereby protecting the integrity of intercellular TJ during mastitis." (PMID 40552401, 2025). "Furthermore, PANoptosis activation is the main pathway and an effective therapeutic target during mastitis disease progression, and GSDMD activation is a key factor contributing to the BMB damage during mastitis, while C3Gal can inhibit its NT activity." (PMID 40552401, 2025). "PANoptosis activation is an effective therapeutic target during mastitis progression, and Gasdermin D activation is key factor contributing to blood milk barrier damage during mastitis, while cyanidin 3‐O‐galactoside can inhibit these targets to exert a protective effect." (PMID 40552401, 2025). "In conclusion, these results suggest that GSDMD activation is a key factor in exacerbating the severity of mastitis and BMB damage, and that inhibition of GSDMD activation protects the TJ integrity during mastitis." (PMID 40552401, 2025). "Notably, GSDMD is a key execution protein in the PANoptosis pathway and C3Gal does not inhibit its cleavage to produce NT.[8b,c] Therefore, we hypothesized that C3Gal alleviated the BMB damage and GSDMD‐NT activity during mastitis." (PMID 40552401, 2025). "The results showed that, unlike in the mastitis group, no significant redness and swelling were observed in the mammary glands of TLR4−/− and GSDMD−/− mice." (PMID 40552401, 2025). "C3Gal was found to bind GSDMD proteins and inhibit their NT activity, thereby protecting the integrity of the BMB during mastitis rather than inflammatory factors." (PMID 40552401, 2025).
Multiple Organ Failure (2 papers, 2021 to 2025). A progressive condition usually characterized by combined failure of several organs such as the lungs, liver, kidney, along with some clotting mechanisms, usually postinjury or postoperative. "Excessive GSDMD activation could trigger the systemic activation of coagulation cascades, culminating in DIC, multiple organ failure, and lethality." (PMID 33854044, 2021).
peritonitis (2 papers, 2022 to 2023). Inflammation of the peritoneum (tissue that lines the abdominal wall and covers most of the organs in the abdomen). "In an E. coli-peritonitis model, GSDMD deficiency improved host defense by delaying neutrophil cell death." (PMID 37664463, 2023). "Of note, in an E.coli-induced peritonitis model GSDMD deficiency led to improved host defense by delaying neutrophil death and increased levels of proinflammatory cytokines in the peritoneal cavity, showing an anti-inflammatory effect of ELANE-dependent GSDMD activation in neutrophils." (PMID 37664463, 2023).
pulpitis (2 papers, 2021 to 2026). Inflammation of the dental pulp. "In this study, we first revealed that cytosolic mtDNA promotes pulpitis progression through GSDMD-mediated pyroptosis." (PMID 34887391, 2021). "In this study, high gasdermin D (GSDMD) expression was detected in human pulpitis." (PMID 34887391, 2021).
rectum adenocarcinoma (2 papers, 2023 to 2025). An adenocarcinoma arising from the rectum. "When analyzing progression-free survival (PFS), GSDMD was positively correlated with Rectum adenocarcinoma (READ), and negatively correlated with ACC, LGG, and others." (PMID 40491921, 2025).